PDCL2 (phosducin like 2)
Description:
Essential for male fertility, spermiogenesis and acrosome formation.
Synonyms: GCPHLP
Tractability: Small molecule: it has a high-quality binding pocket.
Gene: Protein-coding gene on chromosome 4 (55,556,519 to 55,592,245, reverse strand). Ensembl gene ENSG00000163440.
Subcellular location: Endoplasmic reticulum
Subcellular location (Human Protein Atlas): Microtubules; Centrosome
Gene Ontology:
Biological process: acrosome assembly; protein folding; spermatid development
Cellular component: cytoplasm; endoplasmic reticulum
Genetic constraint (gnomAD): Loss-of-function variants: 8 observed, 11.38 expected, observed/expected ratio (o/e) 0.7, 90% interval 0.41 to 1.27. The upper end of that interval is the gene's LOEUF score, 1.27, which puts it in group 5 of 6, group 1 being the genes least tolerant of losing a copy. Missense variants: 155 observed, 158.53 expected, observed/expected ratio (o/e) 0.98, 90% interval 0.86 to 1.12. Synonymous variants: 40 observed, 47.23 expected, observed/expected ratio (o/e) 0.85, 90% interval 0.66 to 1.1.
Homologues: Orthologues: chimpanzee PDCL2 (99% identical), macaque PDCL2 (97% identical), rabbit PDCL2 (93% identical), dog PDCL2 (92% identical), pig PDCL2 (88% identical), mouse Pdcl2 (87% identical), rat Pdcl2 (86% identical), guinea pig PDCL2 (71% identical), Drosophila melanogaster viaf (41% identical), Caenorhabditis elegans mau-8 (17% identical), Drosophila melanogaster CG7650 (17% identical). Paralogues in human: PDCL3 (59% identical), TXNDC9 (26% identical), PDCL (24% identical), PDC (22% identical).
Diseases named in the same sentence as PDCL2 in open-access papers:
PDCL2 is named in the same sentence as 8 diseases in open-access papers, as found by Europe PMC text mining. Sharing a sentence is not in itself a finding about the gene and the disease. The quoted sentences say what the papers report.
Globozoospermia (2 papers, 2023 to 2024). Any structural anomaly of the acrosome resulting in a round sperm head. "We recently found that male PDCL2 knockout mice are sterile due to globozoospermia caused by impaired sperm head formation, indicating that PDCL2 is a potential target for male contraception." (PMID 36209044, 2023).
Infertility (2 papers, 2022 to 2024). "A functional deficiency of the PDCL2 gene causes abnormal acrosome biogenesis during spermiogenesis and the loss of sperm motility, leading to infertility." (PMID 39126002, 2024). "Mechanistically, PDCL2 can interact with the CCT complex, and dysfunction in this complex might lead to infertility in Pdcl2−/− male mice." (PMID 36253364, 2022).
kidney cancer (1 paper, 2021). Primary or metastatic malignant neoplasm involving the kidney. "It is noteworthy that high expression of PDCL2 appears to be associated with decreased survival of kidney cancer patients." (PMID 33426787, 2021).
male infertility (1 paper, 2022). The inability of the male to effect fertilization of an ovum after a specified period of unprotected intercourse. "To investigate how PDCL2 deficiency leads to male infertility, we examined sperm squeezed from the cauda epididymis of Pdcl2+/+, Pdcl2+/−, and Pdcl2−/− mice and quantified the obtained sperm samples." (PMID 36253364, 2022). "Collectively, these findings confirm that Pdcl2 knockout leads to male infertility in mice and that PDCL2 may function as a chaperone to promote protein folding during spermiogenesis." (PMID 36253364, 2022).
renal carcinoma (1 paper, 2021). A carcinoma arising from the epithelium of the renal parenchyma or the renal pelvis. "This demonstrates that PDCL2 protein signals for renal cancer are reproducible using custom‐made and commercial TMAs." (PMID 33426787, 2021).
teratozoospermia (1 paper, 2022). "Patients with teratozoospermia exhibit low phosducin-like protein (Pdcl2) expression." (PMID 36253364, 2022). "Interestingly, patients with teratozoospermia exhibit low levels of phosducin-like protein 2 (Pdcl2) expression." (PMID 36253364, 2022).
type 2 diabetes mellitus (1 paper, 2017). A type of diabetes mellitus that is characterized by insulin resistance or desensitization and increased blood glucose levels. "Five polymorphisms—rs139421991 of CAT, rs189305583 of PDCL2, rs138313632 of RUFY1, rs139012426 of LOC100505549, and rs76974938 of C21orf59—may be novel determinants of type 2 diabetes mellitus." (PMID 29113320, 2017).
PDCL2 also shares sentences with these, for which no sentence is quoted: cancer (1 paper).